WSB1 (WD repeat and SOCS box containing 1)
Diseases named in the same sentence as WSB1 in open-access papers (continued):
Sharing a sentence is not in itself a finding about the gene and the disease.
cancer (continued). "To uncover the molecular mechanism of miR-592 HCC inhibitory potential, we hypothesized that decreased WSB1 expression by miR-592 would reduce the HIF-1α level in HCC because HIF-1α signaling has been demonstrated to be enhanced by WSB1 in various cancers." (PMID 27153552, 2016). "In this context, downregulation or decreased function of WSB1 would be expected in cancer cells, however, participation of WSB1 in ubiquitin-mediated degradation of a tumor suppressor gene such as VHL may also demonstrate a role for WSB1 as an oncoprotein." (PMID 27542736, 2016). "These activities suggest a role for wsb1 in cancer cell proliferation and metastasis." (PMID 27542736, 2016). "Hypoxia also induced significant expression of the wsb1 gene in cancer specimens." (PMID 27542736, 2016). "Data on WSB1 regulation support the hypothesis that activation of stress-response mechanisms helps cancer cells establishing metastases and suggest relevance to cancer development of other genes overexpressed in xenografts." (PMID 18575577, 2008). "Aside from its initial characterization in developmental biology, recent studies show WSB1 has an intriguing role in the regulation of thyroid homeostasis, immune responsiveness, glycolysis and hypoxia, as well as potentially influencing the development or growth of cancer." (PMID 27542736, 2016). "WSB1, an E3 ligase component, promotes hypoxia-inducible factor 1α (HIF-1α) degradation under normoxia, which promotes cancer invasion and metastasis." (PMID 40375984, 2025). "Its close paralog, WSB1, is induced by hypoxia and can form a CRL5WSB1 complex that promotes cancer metastasis by inducing VHL degradation." (PMID 40699886, 2025). "Thus it is possible that WSB1 may promote HCC progression through altering cancer cell metabolism." (PMID 27153552, 2016). "In addition, the genes characterizing classical phenotypes of cancer stem-like (ASCL2), hypoxia (WSB1) and apoptosis (ATF3) were all highly expressed in the tumor or stromal region, suggesting cell differentiation programs." (PMID 38729966, 2024). "Since DAP3 is widely overexpressed in cancer cells, such DAP3-driven stabilization of WSB1 mRNA transcripts may be a key step in tumor initiation." (PMID 35379802, 2022). "Overexpression of WSB1 in WT EC109 cells promoted tumorigenesis in vitro and in vivo when compared to WT cells expressing empty vector control, indicating the oncogenic role of WSB1 in cancer cells." (PMID 35379802, 2022). "Indeed, we observed that the miR-592 knockdown-mediated upregulation of the WSB1 level increased the expression of HIF-1α, which plays an important role in critical aspects of HCC cancer biology, especially glucose metabolism." (PMID 27153552, 2016). "WD repeat and SOCS box containing 1 (WSB1) was recently identified as a new member of the suppressor of cytokine signaling (SOCS) box protein family, and its expression was upregulated in multiple types of human cancers." (PMID 27153552, 2016).
tumor (16 papers, 2008 to 2025). "WSB1 was reported to suppress hypoxia-induced cell apoptosis in tumor cells, and our study demonstrated that WSB1 restrained IR-caused cardiac dysfunction and cardiomyocyte death, but its effects on ROS or oxidative stress reaction remained unclear." (PMID 38395742, 2024). "For instance, sc-seq has uncovered malignant cell subclusters enriched in genes associated with histone deacetylase (HDAC) inhibitor response (ATF3, CAV1), inflammation (LXN, PGM1), and hypoxia-linked tumor metastasis (WSB1), highlighting their importance in tumor progression." (PMID 41450739, 2025). "Moreover, WSB1 expression has been associated with tumor incidence and metastatic potential in pancreatic and hepatocellular cancer." (PMID 37628609, 2023). "Through its E3 ligase activity, WSB1 can promote the ubiquitination and proteasomal degradation of the von Hippel‒Lindau (pVHL) tumor suppressor and induce cancer invasion and metastasis." (PMID 38177295, 2024). "Acting as an E3 ligase, WSB1 was reported to play a protective role in tumor cells and non-tumor cells by catalyzing the ubiquitination and proteasomal degradation of substrate molecules." (PMID 38395742, 2024). "We classified UM tumor cells into six distinct subclusters based on marker gene expression: C0 WSB1+ TCs, C1 EEF1A1+ TCs, C2 HSPB7+ TCs, C3 XIST+ TCs, C4 GNG11+ TCs, and C5 PCOLCE+ TCs." (PMID 39635521, 2024). "The WSB1 gene is a transcriptional target of numerous onco-proteins and dysregulation of transcriptional factors can in turn contribute to tumor progression by abnormal activation of targeted oncogenes." (PMID 37628609, 2023). "The WSB1 gene is a transcriptional target of numerous oncoproteins, and its dysregulation can contribute to tumor progression by abnormal activation of targeted oncogenes." (PMID 37628609, 2023). "Considering that WSB1 plays an important role in tumor metastasis and tumor cell proliferation, clinically relevant drugs targeting the WSB1 axis as inhibitors are still being investigated." (PMID 35600960, 2022). "A recent study showed the correlation of copy number and overexpression of WSB1 on 17q11.1, more common in stage 4s and locoregional NB compared to stage 4 tumours." (PMID 19192278, 2009). "The important point is that stress-induced modulation by alternative splicing of the expression of WSB1 isoforms is very similar to what we observed during xenograft tumor progression." (PMID 18575577, 2008). "Dysfunction of WSB1 is related to tumor initiation and progression." (PMID 38177295, 2024). "There are many research studies about WSB1 regulating tumor progression." (PMID 35600960, 2022). "Interestingly, when patient cohorts were clustered by subtype or HR status, WSB1 expression was significantly lower in the most aggressive tumours, such as HR− and TNBC." (PMID 29540773, 2018). "Interestingly, both groups discovered that tumor hypoxia modulated the splice form of the wsb1 mRNA created." (PMID 27542736, 2016). "Whether the stress-induced changes in WSB1 isoform expression is necessary for tumor development, which would make it a potential therapeutic target, remains however to be investigated." (PMID 18575577, 2008). "WSB1 WD repeat and SOCS box-containing protein 1 (WSB1) is an e3-ubiquitin ligase that can promote ATM ubiquitination and degradation, leading to tumor progression." (PMID 38352299, 2023). "The published evidence now strongly suggests that in hypoxia, WSB1, through diverse mechanisms such as protection of HIF-1 through downregulation of VHL, HIPK2 and/or RhoGDI2, contributes to tumor metastasis." (PMID 27542736, 2016). "In addition, WSB1 is transcriptionally activated by hypoxia inducible factor (HIF)-1, and also stabilizes HIF-1 protein molecule in tumor cells with hypoxic condition." (PMID 38395742, 2024). "It is plausible that WSB-1 regulation by HIF has a role in earlier stages of tumour development, which are not reflected in the later stage patient samples analysed." (PMID 29540773, 2018).
tumor (continued). "In contrast to WSB1 expression, which was not different or decreased between normal tissue and tumour tissue, the expression of all these genes was increased in the tumour tissue." (PMID 29540773, 2018). "WSB1 expression was also not significantly altered in tumours when compared to normal tissue." (PMID 29540773, 2018).
infection (2 papers, 2021 to 2025). The state of being infected such as from the introduction of a foreign agent such as serum, vaccine, antigenic substance or organism. "Infection with A. lumbricoides was associated with increased WSB1 methylation (P = 0.031)." (PMID 33692795, 2021). "SNVs in WSB1 (rs7213148 and rs8065359) and IL21R [rs115350516 (A allele) and rs3093308 (T allele)] were associated with increased production of A. lumbricoides-specific IgE and could be potentially linked to greater resistance to infection." (PMID 33692795, 2021). "For S. aureus infection, WSB1 (ubiquitination-related) was downregulated in S1, while only DDIT4 was downregulated in S3, suggesting broader impacts on stress pathways at higher infection concentrations." (PMID 40771952, 2025).
WSB1 also shares sentences with these, for which no sentence is quoted: osteosarcoma (3 papers); breast tumour (1); chordoma (1); colon adenocarcinoma (1); esophageal carcinoma (1); glioblastoma (1); lung adenocarcinoma (1); myeloma (1); ovarian carcinoma (1); renal carcinoma (1); stomach adenocarcinoma (1); thyroid disease (1); viral infection (1).